NGF (nerve growth factor)
Diseases named in the same sentence as NGF in open-access papers (continued):
Sharing a sentence is not in itself a finding about the gene and the disease.
neurodegenerative disease (131 papers, 2007 to 2026). A disorder of the central nervous system characterized by gradual and progressive loss of neural tissue and neurologic function. "Neurodegenerative diseases are frequently associated with impaired synthesis or release of neurotrophic factors, including NGF." (PMID 41516320, 2025). "Alterations in BDNF and NGF levels have been associated with Alzheimer's disease, psychiatric disorders, and other neurodegenerative diseases." (PMID 39628974, 2024). "TP53INP2 is highly expressed in sympathetic neuron axons and regulates axon growth by enhancing NGF-TrkA signaling, a pathway implicated mainly in neurodegenerative diseases." (PMID 35682902, 2022). "Among the neurotrophins, NGF has been studied extensively as a drug target owing to its strong association to neurodegenerative diseases." (PMID 26075266, 2015). "Specifically, it is thought that with aging and neurodegenerative disease there is deficient retrograde transport of NGF leading to an up regulation of NGF in specific brain regions to compensate." (PMID 20877209, 2010). "The neurotrophins BDNF and NGF are associated with the maturation, survival, and maintenance of neuron functions in the central nervous system (CNS), and their decrease gives rise to the development of neuronal injury and neurodegenerative diseases." (PMID 39628974, 2024). "NGF belongs to a family of proteins known as neurotrophins, which are responsible for the development, survival, and function of neurons and have been associated with neurodegenerative disease states and symptoms." (PMID 35216124, 2022). "Insufficiency of NGF in the brain is one of the causes of neurodegenerative diseases." (PMID 31649530, 2019). "Moreover, it has been seen that a deficit in NGF is often associated with various neurodegenerative diseases, and in particular, neurodegenerative processes together with neuroinflammation play a key role in the pathogenesis and presence of neuropathic pain." (PMID 30217164, 2018). "Deprivation of NGF may affect the cholinergic neurons, causing neuronal atrophy, memory impairments, and further leads to neurodegenerative diseases, including Alzheimer’s diseases." (PMID 28646880, 2017). "The potentiation of NGF function in the present of ATR volatile oil therefore could be a way for treating neurodegenerative diseases; because the deficiency of NGF in the brain is proposed as one of the causes." (PMID 27685847, 2016). "It would be of interest whether such a “painless” NGF variant can be validated in preclinical and hopefully future clinical trials for neurodegenerative diseases." (PMID 23190582, 2012). "It is largely recognized that proNGF, the NGF precursor, could represent a promising diagnostic biomarker for AD, for the onset of prodromal AD or for other neurodegenerative diseases, but almost nothing is known concerning its potential relationship to FTD." (PMID 38332808, 2023). "An imbalance between the NGF-dependent, TrkA-mediated survival, the growth actions, and the p75NTR-mediated activation of apoptosis/growth inhibitory pathway is causally associated with the onset and/or development of several neurodegenerative diseases of both CNS and PNS, including AD and AMD." (PMID 34566573, 2021). "Neurodegenerative diseases could be a cause triggered by deficiency of NGF in the brain." (PMID 31649530, 2019). "Thus, the intake of SBP may relieve neurodegenerative diseases in suffering from a deficiency of NGF in the brain; however, this notion has to be verified by animal study." (PMID 31649530, 2019). "Thus, the intake of ATR could improve those neurodegenerative diseases suffering from a deficiency of NGF in the brain; however, this notion has to be verified by animal study." (PMID 27685847, 2016). "Neurodegenerative diseases could be caused by the deficiency of NGF in the brain." (PMID 27685847, 2016).
neurodegenerative disease (continued). "At the metabolomic level, it has been found to have neuroprotective effects against neurodegenerative diseases by increasing the secretion of neurotrophins, such as brain-derived neurotrophic factor and nerve growth factor." (PMID 39997711, 2025). "Unlike these mushrooms, H. erinaceus remains unparalleled in its ability to stimulate NGF synthesis, making it a promising candidate for neurodegenerative disease treatment and cognitive enhancement." (PMID 40284172, 2025). "Although these studies were insufficient to demonstrate the therapeutic intracerebral use of NGF in neurodegenerative diseases, they laid the foundation for future research into NGF’s clinical applications." (PMID 40649793, 2025). "Although not neurons, they have been used as in vitro neuronal-like models for studies of NGF signaling and neuronal differentiation, as well as models of cytotoxicity, including serum deprivation, toxic molecules, and neurodegenerative diseases." (PMID 40427418, 2025). "NGF has been tried in several neurodegenerative diseases, but its effects have been also evaluated in other neurological conditions." (PMID 40153582, 2024). "Researchers are exploring various approaches to enhance the delivery and effectiveness of NGF in treating degenerative diseases." (PMID 40153582, 2024). "Erinacine C can promote the synthesis of NGF by astrocytes in rodents more effectively compared to epinephrine, a previously known NGF stimulant, suggesting that erinacine C can be potentially used as a treatment for neurodegenerative diseases." (PMID 38539904, 2024). "It is found that neuronal apoptosis induced by the decline of NGF secretion ability of brain neuronal cells leads to neurodegenerative diseases." (PMID 35874807, 2022). "Due to NGF’s low bioavailability and its impermeability through the blood–brain-barrier, it has been considered that the use of NGF as a potential therapeutic agent against neurodegenerative diseases, including AD, was limited." (PMID 35887075, 2022). "For example; in therapeutic approaches of neurodegenerative diseases, MSCs can be genetically engineered to overexpress specific neurotrophic factors like nerve growth factor (NGF) or glial cell line-derived neurotrophic factor." (PMID 35308211, 2022). "Even though neural ingrowth can occur with degenerative disease, the expression of NGF, TrkA, BDNF, and TrkB by NP cells themselves indicates an independent role played by these neurotrophins apart from neoinnervation." (PMID 35628530, 2022). "Nerve growth factor (NGF) was tethered with polyethersulfone in the fibroblast encapsulation for treating neurodegenerative diseases." (PMID 35214030, 2022). "This brief review will focus mainly on the clinical experience gained to date, regarding the administration of NGF to the brain of patients suffering from neurodegenerative diseases and from the outcomes of neurotrauma." (PMID 34867367, 2021). "Accordingly, searching for compounds with considerably small molecular size and equal or even better neuritogenic activity than NGF is a possible way for neurodegenerative disease medication development." (PMID 34680600, 2021). "Several studies have shown that H. erinaceus mycelium can stimulate the synthesis of NGF for neuroprotection and prevents neurodegenerative diseases." (PMID 34865649, 2021). "In the future, we aim to further optimize the assay to obtain a multiplex measure of both NGF and proNGF, with the goal of measuring the proNGF/NGF ratio in the Alzheimer's continuum and for the differential diagnosis in different neurodegenerative diseases." (PMID 34776928, 2021). "NGF deprivation of these neurons leads to their degeneration, as demonstrated by evidence that the levels of NGF in brain structures are modified in neurodegenerative diseases, including AD." (PMID 33321704, 2020).
neurodegenerative disease (continued). "NGF cannot pass through the blood brain barrier (BBB) because of its physical property, resulting in difficultly in using NGF as a drug to treat neurodegenerative diseases." (PMID 32831994, 2020). "The neurotrophic factor NGF has therefore been considered for treating the neurodegenerative diseases such as AD." (PMID 31790465, 2019). "The results of this study showed that using NGF, as an inducer, hDPSCs can differentiate into cholinergic neurons, which can be used for cytotherapy in degenerative diseases of the nervous system and spinal cord injury." (PMID 32477478, 2019). "Alterations of NGF and BDNF in the brain, and the disrupted binding of NGF and BDNF to their kinase receptors, are both linked to neurodegenerative diseases." (PMID 30223579, 2018). "NGF was the most efficacious neurotrophic factor to induce neuronal differentiation and to prevent atrophy of cholinergic neurons in patients with neurodegenerative diseases." (PMID 29535608, 2018). "NGF and NT-3 exhibited a neuroprotective function with therapeutic potential against neurodegenerative diseases." (PMID 28441758, 2017). "Particularly, in-depth study is needed to shed more light on which phytochemicals regulate neurodegenerative diseases by regulating NGF-TrkA signaling." (PMID 26075266, 2015). "We further show the efficacy of our approach to accurately engineer specific GAG-mediated physiological processes by modulating the NGF/TrkA-mediated neuronal signaling, offering a promising therapeutic strategy for the treatment of neurodegenerative disease." (PMID 28694940, 2015). "NGF-dependent pathway plays a very important role in neonatal development, aging processes, and in the etiopathogenesis of neurodegenerative diseases." (PMID 25841889, 2015). "Difficulties connected with the use of recombinant NGF in the therapy of neurodegenerative diseases prompted the search for new therapeutic strategies." (PMID 25841889, 2015). "In the search for neuroactive compounds that mimic the NGF activity for the prevention of neurodegenerative diseases, the potential medicinal values of culinary and medicinal mushrooms attract intense interest." (PMID 23822837, 2013). "In neurodegenerative disease models, NGF protects cells against oxidative stress by inducing HO1 expression in a phosphatidylinositol 3-kinase-dependent manner." (PMID 24180625, 2013). "Soon after its discovery, in the middle of the twentieth century, it became clear that NGF had great pharmacological potentialities, for the treatment of major central neurodegenerative diseases and of peripheral neuropathies." (PMID 23190582, 2012). "NGF, a neuronal survival molecule that can potentially be used to treat neurodegenerative diseases is a VDR-regulated protein that is affected by VDR suppression." (PMID 21408608, 2011). "Several studies reported a neuroprotective and reparative role of NGF in neurodegenerative diseases." (PMID 17971868, 2007). "By highlighting the ability of H. erinaceus to stimulate NGF synthesis, combat neuroinflammation, and protect against oxidative stress, this review underscores its therapeutic potential in the prevention and management of neurodegenerative diseases." (PMID 40284172, 2025). "However, disappointingly, the depletion of the NGF has led to neurodegenerative diseases and symptoms." (PMID 38791953, 2024). "The level of NGF was decreased during aging and neurodegenerative diseases." (PMID 38751783, 2024). "In any event, the new mechanism described here provides a novel strong rationale to develop therapeutic approaches aimed at increasing the activity of NGF in the brain, as a broad neuroprotective strategy, in the context of different neurodegenerative diseases." (PMID 37143894, 2023). "Whereas NGF/TrkA signaling could function in a neuroprotective role during aging and/or in neurodegenerative diseases, p75NTR could promote apoptosis." (PMID 37808473, 2023).
neurodegenerative disease (continued). "BDNF and Nerve growth factor (NGF) might be appropriate prognostic and diagnostic markers of neurodegenerative diseases." (PMID 37841055, 2023). "NGF is essential for neuronal protection and outgrowth of neurons and also presents a high therapeutic potential for the treatment of Alzheimer’s and other neurodegenerative diseases." (PMID 36559186, 2022). "A reduction in NGF is found in the brains of patients with neurodegenerative diseases." (PMID 36147317, 2022). "Similar to other types of neurodegenerative disease, secretion of NTFs, such as nerve growth factor (NGF) and neurotrophin-3 (NT-3), by MSCs following intracerebral injection could potentiate neuroprotection." (PMID 35842587, 2022). "In view of its strong neuroprotective and regenerative actions both in vitro and in vivo, delivery of NGF to the brain and eye has been always explored with therapeutic purposes for cerebral and extracerebral (retinal) neurodegenerative diseases, including AD and AMD." (PMID 34566573, 2021). "This immunoassay could also be applied to explore in deeper detail the role of NGF precursor in the pathogenesis of neurodegenerative diseases and in physiological conditions." (PMID 34776928, 2021). "However, the mature NGF level is reduced in neurodegenerative diseases, especially AD, leading to NGF insufficiency in patients." (PMID 32308720, 2020). "Nerve growth factor (NGF) and other neurotrophic factors have been found to promote growth and survival of various neuronal populations, and some studies have suggested that decreases in NGF levels are observed in various neurodegenerative diseases, such as PD." (PMID 32842530, 2020). "However, little is known about the use of AEAC treatment of neurodegenerative diseases or their direct effects on NGF secretion using animal models expressing AD pathological features." (PMID 29625607, 2018). "Therefore, low molecular weight NGF mimics from natural or dietary sources have become the center of attention in the search for preventive and therapeutic agents of neurodegenerative diseases." (PMID 28646880, 2017). "Malathion-induced reduction of neuritogenesis, neuronal protein expression, and NGF secretion indicate that malathion may play a role in the induction of neurodegenerative diseases such as AD." (PMID 28487766, 2017). "The present study also showed that 6-shogaol could act as an NGF mimic, which may be beneficial for preventive and therapeutic uses in neurodegenerative diseases." (PMID 28646880, 2017). "This study suggests that 6-shogaol could act as an NGF mimic, which may be beneficial for preventive and therapeutic uses in neurodegenerative diseases." (PMID 28646880, 2017). "In view of NGF being the known disease target, binding between herbal fractions on the chip and NGF can identify potential targets for drug development of treatments for neurodegenerative diseases." (PMID 27453720, 2016). "Importantly, we have successfully applied our approach to identify an effective neuronal promoting agent for selectively modulating the NGF-mediated signaling pathway, offering a potential therapeutic strategy for the treatment of neurodegenerative disease." (PMID 28694940, 2015). "Thus, quinic acid from A. scaber extract ameliorates neurodegenerative diseases by enhancing the free radical scavenging system and protecting neurons from free radicals and potentiating neurite outgrowth by acting as an NGF mimetic." (PMID 26075266, 2015). "Hence, the potential medicinal values of culinary and medicinal mushrooms have attracted intense interest in the search for pharmacological compounds that mimic the NGF activity in the prevention of neurodegenerative diseases." (PMID 23822837, 2013). "However, the development of an NGF-based therapy for neurodegenerative diseases remains a considerable challenge, due to limited access of NGF to the brain and to its potent nociceptive actions in animals and humans." (PMID 22666365, 2012).
neurodegenerative disease (continued). "There are a great deal of interests in whether NGF can prevent neurodegenerative diseases, or promote central nervous sysytem repair." (PMID 23554704, 2011). "In particular, the increased production of NGF and other trophic factors in CNS during neurodegenerative disease may suppress inflammation by switching the immune response to an anti-inflammatory, suppressive mode." (PMID 17971868, 2007). "By characterizing DMSO-NGF interactions, this study provides valuable insights for the development of NGF-targeting small molecules, supporting their potential as effective alternatives to monoclonal antibodies for treating pain, inflammation, and neurodegenerative diseases." (PMID 40733301, 2025). "In addition, NGF plays an important role in neurodegenerative diseases and neuronal survival." (PMID 38672292, 2024). "However, the reduction of NGF in the brain occurs during aging and in neurodegenerative diseases." (PMID 36147317, 2022). "Therefore, activation of NGF signaling could have the potential for the treatment of neurodegenerative diseases." (PMID 35327616, 2022). "Thus, D. cochinchinensis extracts may be used to treat neurodegenerative diseases in those with insufficient amounts of NGF." (PMID 36147317, 2022). "Overall, these evidences suggest that NGF-based therapy could improve neurological outcomes that are related to dysfunctions of the central cholinergic system, both in neurodegenerative diseases and after TBI, normalizing APP and tau metabolism in TrkA-expressing cells." (PMID 34867367, 2021). "Therefore, the NGF-potentiating effect of isorhamnetin could be considered as a new direction in developing health food supplements to help the recovery of neurodegenerative diseases relating to NGF insufficient." (PMID 22761636, 2012). "Nerve growth factor (NGF), a neurotrophin that binds to TrkA receptors, plays a critical role in neuronal survival and regeneration, making it an ideal ligand for neurodegenerative disease therapies." (PMID 40430951, 2025). "For example, intranasal delivery of nerve growth factor (NGF) has shown good therapeutic potential in treating traumatic brain injury (TBI) and other neurodegenerative diseases such as AD and PD, providing new insights for the clinical application of NGF." (PMID 40574087, 2025). "Intranasal delivery has been used in clinical studies to deliver small-molecule agents to the brain, such as nerve growth factor (NGF) and brain-derived neurotrophic factor (BDNF), thus treating neurodegenerative diseases." (PMID 40606141, 2025). "Vitamin D induces the synthesis of nerve growth factor (NGF), which promotes the development, maintenance, and survival of specific neurons, playing a key role in neurodegenerative diseases where neuronal survival is compromised." (PMID 40806275, 2025). "Decreased Nerve Growth Factor (NGF) and Brain-Derived Neurotrophic Factor (BDNF) levels have been described in neurodegenerative diseases." (PMID 36579579, 2022). "ABG-001, a biologically active small molecule with excellent neuritogenic activity similar to NGF on PC12 cells, has significant potential for drug development to treat neurodegenerative diseases." (PMID 34680600, 2021). "Firstly, nerve growth factor (NGF) contributes to the survival, regeneration, and death of neurons during aging and in neurodegenerative diseases such as AD." (PMID 34198788, 2021). "Overall, present and previous data envisage the in vivo preclinical studies with hNGF1–14 peptides as potent and selective NGF mimetics, and TrkA agonists for CNS and PNS in age-related or inflammation-driven human neurodegenerative diseases." (PMID 32024191, 2020). "In our previous research, DPCM contained many neurotrophic factors such as NT-3 and nerve growth factor (NGF) and contributed to neuroprotective effects against neurodegenerative diseases." (PMID 32457568, 2020).